TNF (tumor necrosis factor)
Diseases named in the same sentence as TNF in open-access papers (continued):
Sharing a sentence is not in itself a finding about the gene and the disease.
tumor (continued). "This drug, called NGR-TNF, consists of a TNF molecule fused to the Cys-Asn-Gly-Arg-Cys-Gly (CNGRCG) peptide (called NGR), a ligand of aminopeptidase N (CD13)-positive tumor blood vessels." (PMID 35890309, 2022). "Th1 cells can coordinate cytotoxic T lymphocytes and NK cells to exert anti-tumor effects by secreting multiple cytokines (IFN-γ, TNF-α and IL-2)." (PMID 36776357, 2022). "IL-17, IL-21, IL-22, TNF-α and IL-6 are also produced in excess in individuals with CRC and synergistically promote tumor growth." (PMID 35739324, 2022). "The increased TNF-α and decreased TGF-β secretion in Hmga2-KO tumor tissues was further confirmed by ELISA in both MC38 and CT26 subcutaneous tumor models." (PMID 34976223, 2022). "And macrophages will differentiate into M1 cells, mainly playing roles in promoting inflammation, sterilization, and anti-tumor, stimulated by factors such as TLR, TNF-α, IFN-γ, CSF2." (PMID 35386701, 2022). "Cytotoxic activity and the production of TNFα and IFN-γ are the main mechanisms of the CD8+ T cell-mediated tumor cytotoxic effect." (PMID 36339614, 2022). "Supplementing conjugated linoleic acid decreased the levels of TNF-α, IL-1β, hsCRP, MMP-2 and MMP-9, which are biomarkers of tumor aggression and angiogenesis." (PMID 36776395, 2022). "The bispecific and combination CAR-T cell strategies showed dramatically higher TNF-α, IL-2, and IFN-γ levels than monospecific CAR-T cells upon tumor cell stimulation." (PMID 35317524, 2022). "Among them, we paid special attention to multiple immune pathways, including the inflammatory response, interferon gamma response, TNF-a signaling pathway and IL-6/JAK/STAT3 signaling, all of which had been shown to be closely related to tumor development." (PMID 35991547, 2022). "The mRNA levels of INOS, TNF-α, IRF5, IL-10, TGM2, and Arg-1 in the blood of tumor-bearing mice treated with the exosomes were detected by qRT-PCR." (PMID 35600340, 2022). "On the other hand, there are considerable evidence that TAMs induce tumor chemotherapy resistance through the release of inflammatory cytokines and chemokines such as IL-6, CCL18, TNF-α, CCL2, and CXCR4." (PMID 36679900, 2022). "- TNF-α: TNF-α increases the expression of intracellular adhesion molecule−1 (ICAM-1), a receptor required for leukocyte adhesion and tumor invasion." (PMID 35252243, 2022). "In particular, inflammatory factors secreted after a surgical intervention such as IL-8, TNF, and CCL2 can promote neutrophil infiltration in addition to SDF1 and plasminogen activator inhibitor 1 secreted by tumor cells." (PMID 35311140, 2022). "Meanwhile, the activated CD8 T cells can directly kill tumor cells or mediate cytotoxic antitumor immune responses by producing granzyme or perforin, IFN-γ, and tumor necrosis factor." (PMID 36568384, 2022). "Research has shown that a higher level of TNF-α, COX-2, and Bcl-xL implies that tumours have a rapid growth rate, and in some cases, indicates severe aggressiveness, metastatic behavior, and poor prognosis." (PMID 35386216, 2022). "Another study on multiple tumors showed that vvDD-IL-23 can promote the expression and release of Th1 chemokines and some anti-tumor factors, which contained IFN-γ, as well as tumor necrosis factor-α (TNF-α), IL-2, perforin, and granzyme B (GzmB)." (PMID 36090998, 2022). "Adipocytes produce several paracrine and endocrine factors known as adipocytokines, including leptin, adiponectin, tumor necrosis factor (TNF)-α and interleukin 6, potentially affecting tumor growth." (PMID 35233007, 2022). "Among the inflammatory cytokines are (IL)-1, IL-6, TNF-a, and IFN-g, which are believed to promote angiogenesis and tumor growth and survival, altering nutrient metabolism, leading to malnutrition." (PMID 35457471, 2022). "At the same time, CD4+ T cells themselves can produce cytokines to participate in the suppression of tumor cells, such as γ-interferon (IFN-γ), tumor necrosis factor-α (TNF-α), and IL-17." (PMID 35454171, 2022).
tumor (continued). "The tested stimuli included tumor promoter PMA, inflammatory response activators TNF-α and TLR ligands, and stressors H2O2 and UVB." (PMID 35185556, 2022). "TNF-α is reported to increase EMT and CSC transition in various tumor cell types and increase cancer transformation, proliferation, and angiogenesis." (PMID 35565306, 2022). "The introduction of recombinant KLK6 protein in KLK6−/− mice rescued the production of TNF-α and CXCL1, tumor growth, and metastasis." (PMID 36552865, 2022). "Nevertheless, is well-known that MCs through releasing IL-1, IL-4, IL-6, IL-8, TNF-α, IFN-γ, TGF-β, MCP-3, MCP-4, leukotriene B4 (LTB4) and chymase can contribute to inflammation, inhibition of tumour cell growth, and induction of tumour cell apoptosis." (PMID 35406451, 2022). "In contrast to the effect of celecoxib on tumor lysate induced DCs, we here show that celecoxib reduced TLR-induced production of IL-10, IL-12, TNF-α, and IL-6." (PMID 36227963, 2022). "In our investigation, we explored the use of three cytokines, TNFα, IL12 and IL15, all of which involve cell‐mediated tumour killing and provide promising results when TPA is used as a delivery method." (PMID 35758207, 2022). "CIITA-Exo enhanced the splenocyte proliferation and IL-2 secretion, and induced inflammatory cytokines (such as TNF-α and IL-12) mRNA production, so that CIITA-Exo had a more potent anti-tumor immune response compared to control Exos." (PMID 36733388, 2022). "This is achieved as γδ T cells do not only induce apoptosis through cytotoxic factors such as granzymes or perforin, but also tumor cell senescence through the production of IFN-γ and TNF." (PMID 35326515, 2022). "NK cells can also respond to tumor cell-derived growth factor and secrete cytotoxic cytokines, such as IFN-γ and TNF-α, as well as proinflammatory chemokines to induce tumor cell growth arrest." (PMID 35920986, 2022). "While we observed significantly reduced fractions of tumor-infiltrating MHC-IIlow macrophages and monocytes, serological levels of TNF-α restored in lung tumor-bearing mice." (PMID 35493461, 2022). "CRC treatment with chemotherapeutic agents induces the synthesis of cytokine TNF-α, which in turn triggers the paracrine release of CXCL2 and results in tumor promotion and chemo-resistance." (PMID 35954156, 2022). "Wogonin can promote the apoptosis of tumor cells, enhance the toxicity of TNF-α and TRAIL to tumor cells, block the tumor cell cycle, inhibit tumor angiogenesis, and cooperate with chemotherapeutic drugs through ROS and Ca2+-mediated signaling pathways." (PMID 35178099, 2022). "From the concentrations measured in the supernatant, we found that CAR-T cells from all three sources secreted higher levels of IL-2, TNF-α, and IFN-γ than WT T cells after coculture with Nalm6-GL tumor cells." (PMID 35965561, 2022). "Levels of periostin, VEGF-A TNFα, IFN-γ, IL-1β and IL-17 were measured using ELISA tests, MVD was assessed on CD34-stained specimens, tumor budding was evaluated on H + E slides, and these data were compared with clinicopathological features of the patients." (PMID 35056404, 2022). "On the 14th day after administration, compared with the control group, the hydrogel vaccine maintained a higher level of tumor necrosis factor (TNF) in the serum, indicating that it promoted the direct killing of the tumor." (PMID 35745954, 2022). "While tumor-infiltrating pDCs possess immunosuppressive properties, the ability of pDCs to produce type I IFN and TNF-α indicates their antitumorigenic potential." (PMID 35629346, 2022). "Like ZA, this molecule has been shown to enhance the sensitivity of tumour cells to Vδ2 killing and enhances Vδ2 production of IFN-γ, TNF, granzyme B and perforin." (PMID 36713444, 2022).
tumor (continued). "A study showed that TNF-α derived from M2TAMs promotes EMT and tumor stem cell properties in hepatocellular carcinoma cells via the Wnt/β-catenin pathway." (PMID 35965509, 2022). "The five TNFSF ligand transcripts were differentially expressed by all these subsets, with tumor-infiltrating germinal cells expressing the highest levels of TNF, LTA, TNFSF10 and LTB, and tumor-infiltrating plasma cells expressing the highest levels of FASLG." (PMID 35392082, 2022). "We found that the number and proportion of CD8+ T lymphocytes, CD8+TNFα+T lymphocytes and CD8+INFγ+ lymphocytes were significantly increased in tumor-bearing mice treated with fruquintinib or sintilimab alone or combination therapy." (PMID 35371995, 2022). "Tumor necrosis factor-α (TNF-α) and interferon-γ (IFN-γ) are two main cytokines produced by activated NK cells, orchestrating anti-tumor immune responses." (PMID 35031075, 2022). "In 1,4-dihydroxy quininib treated UM explants, a significant negative correlation was observed between IL-13 secretion and tumour thickness; IL-1β secretion and tumour dimensions (LUD and LUH); IL-8 secretion and tumour dimensions; and TNF-α secretion and LUH." (PMID 36698840, 2022). "The inhibition of the TNF-α/NF-kB pathway by Kanglaite inhibits the EMT and slows tumor progression." (PMID 35884974, 2022). "IFN-γ and tumor necrosis factor-α (TNF-α) are often regarded as the cytokines secreted by cytotoxic T cells, which contribute to T-cell killing and fight against tumor progression." (PMID 34875483, 2022). "Because EMT is driven by growth factors such as TNF and interleukins as well as inter- and intracellular communication, the tumor microenvironment (TME) exerts a significant influence on tumor EMT." (PMID 36552039, 2022). "These NP yielded downregulation of PD-1 expression in primary human tumor-infiltrating leukocytes (TIL) obtained from breast cancer specimen, and enhanced their tumor cell killing activity in vitro, accompanied by elevated IFN-γ and TNF-α contents." (PMID 35693776, 2022). "Cytokines are also critical for anti-tumor response, as for T cells to exert their cytotoxic effects on tumor cells, other cytokines, including interferon (IFN)- γ and tumor necrosis factor (TNF)-α, must also be secreted." (PMID 36298592, 2022). "MiR-155 induced by inflammatory cytokines, such as IL-1β and TNFα, mediates mesenchymal transition of GBM tumor cells and GBM growth." (PMID 35572545, 2022). "The stepwise tumor immunity events are eventually executed through CD8+ T cell‐directed tumor cytolysis, targeting cancer cells by granule exocytosis and Fas ligand (Fas L)‐mediated apoptosis as well as IFN‐γ or TNFα -induced cytotoxicity." (PMID 36059511, 2022). "Pro-inflammatory extracellular ATP (eATP) is one of the crucial regulators of the tumor-induced activation of EC, as cancer cells can increase its basal release using EC via cytokines, such as TNF-α (tumor necrosis factor-alpha)." (PMID 35628582, 2022). "Specifically, TNFα can reduce muscle ATP synthesis and decrease mitochondrial activity in LLC1 tumor bearing mice." (PMID 35441960, 2022). "Conversely, IL-1, IL-6, tumor necrosis factor (TNF)-α, and tumor growth factor-β (TGF-β) can trigger tumor progression." (PMID 35765486, 2022). "Then, progranulin antibody therapy increases levels of granzyme B, TNF, IFN-γ, and CD8+ T cells, reviving CD8+ T cell anti-tumor cytotoxicity." (PMID 36300110, 2022). "Th1 cells, IFN-γ, and TNFα regulate M1 macrophages to enhance antigen presentation on the major histocompatibility complex (MHC) to exert anti-tumour immune response." (PMID 36248850, 2022). "Th1 cells mainly produce cytokines that defend against the tumor, such as TNF-a and IFN-γ, while Th2 cells promote tumor growth by releasing cytokines that inhibit the antitumor immune responses." (PMID 36046648, 2022).
tumor (continued). "The stimulation with TNF-α would then induce pyroptosis instead of apoptosis in hypoxia, explaining the mechanism of how TNF-α induces tumor necrosis in hypoxia." (PMID 35565420, 2022). "To study tumor-specific CD4+ T-cell dysfunction, we measured the expression of exhaustion markers, as well as IFN-γ, TNF-α, and IL-2 production of recovered SMARTA cells." (PMID 35784297, 2022). "M1s synthesize pro-inflammatory cytokines such as tumor necrosis factor-α (TNF-α), IL-1, IL6, IL-12, IL-23, and reactive nitrogen and intermediate oxygen compounds, and thus inhibit tumor development." (PMID 36611344, 2022). "Many tumor cells can also produce PTHrP, IL-1, IL-6, PGE2, TNF, CSF-1, and other factors not only to promote their own survival, but also to increase the production of osteoclasts at the same time." (PMID 36230816, 2022). "We next used cytokine bead arrays to examine the secretion of TNF and IFNγ by sgNkg7 and sgNT OT-I T cells during synapse with MC38-OVA tumor targets, as these are key cytokines that contribute to the anti-tumor effector activity of CD8+ T cells." (PMID 35874669, 2022). "A triple system isoDGR/Au/IL-12+TNF alone was slightly less effective than free DOX, but a combined treatment with said AuNPs + DOX resulted in considerable tumor suppression." (PMID 36430214, 2022). "M1 macrophages secrete tumor necrosis factor-α (TNF-α), which can kill and inhibit the growth of tumor cells." (PMID 35634419, 2022). "On the one hand, the innate and adaptive immune cells like M1 macrophages and natural killer (NK) cells can clear the tumor cells and promote their senescence by secreting IFN-γ and TNF-α, thus limiting tumor growth." (PMID 35898492, 2022). "Compared to PANC1 and BxPC3 tumor, coro1a: GFP+ cells from AsPC1 xenografts expressed a low level of TNF-α and IL-12, and a higher level of IL-10." (PMID 35742884, 2022). "We detected more abundant levels of sICAM-1, CXCL10, CXCL1, CCL5, TIMP-1 and TNFα in tumours treated with VV-αCEA TCE, compared to tumours treated with VV-CTRL or PBS." (PMID 36405739, 2022). "Ferroptotic DCs lose the ability to secrete TNF and IL-6, express MHC class I, and induce IFN-γ secretion by CD8+ T cells, thus limiting their anti-tumor abilities." (PMID 35372083, 2022). "PMCs prevent initial tumor cell invasion by secreting TNFα, CRC cells secrete IL‐6, and IL‐10 converts these anti‐tumorigenic PMCs to a pro‐tumorigenic M2 phenotype favoring tumor progression." (PMID 35791509, 2022). "Activated γδ T-cells and quiescent NK cells play anti-tumor roles by inducing the release of cytotoxic molecules and cytokines such as interferon-γ (IFN-γ) and tumor necrosis factor-α (TNF-α) on cancer cells." (PMID 36226174, 2022). "This process begins prior to the arrival of tumor cells when cytokines secreted by the primary tumor, such as VEGF, TNF-alpha, and TGF-beta, recruit immunosuppressive myeloid cells to the bone." (PMID 35159026, 2022). "Effector CD8+ T cells, also named cytotoxic T lymphocytes (CTL), play the most significant adaptive tumor-killing effects in TME by releasing cytotoxic perforins, granzymes, and cytokines such as interferon (IFN)-γ and tumor necrosis factor-α." (PMID 36300110, 2022). "In conclusion, NK cells are classified as innate immune cells with cytotoxicity against tumor cells and virus-infected cells, and also secrete several signaling substances such as IFN-γ, TNF-α, and chemokines." (PMID 35001010, 2022). "PMN-MDSC actively communicate with cancer cells through inflammatory mediators and growth factors such as IL8, IL17a, CCL2, TNFα, BV8, VEGFα, and TGFβ plays important roles in various aspects of tumor cell dissemination, invasion, and angiogenesis." (PMID 35504900, 2022). "Co-culture of T cells with BC cells revealed that miR-383-5p promoted the expression of INF-γ, IL-2, and TNF-α, while reducing the expression of IL-10 and TGF-β, indicating the ability of miR-383-5p to block tumor-induced immunosuppression." (PMID 36313570, 2022).
tumor (continued). "M1 macrophages (CD86+ and CD80+) release pro-inflammatory cytokines (e.g., IL-6, IL-12, TNF-α) to play an anti-tumor role, while M2 macrophages (CD206+) release pro-tumor cytokines (e.g., IL-4, IL-10, IL-13) to promote tumor progression and metastasis." (PMID 35432300, 2022). "Growing pieces of evidence demonstrate the important implications of tumor necrosis factor-alpha (TNF-α) in gastric carcinogenesis, which is an essential proinflammatory cytokine in the tumor microenvironment of GC and the main cytokine of cancer pain." (PMID 35719369, 2022). "Inflammatory cytokines, such as, interleukin, tumor necrosis factor and TGF-β, play key roles in tumor progression and promotion of early metastasis." (PMID 35846349, 2022). "Besides, the conjugate showed a high antitumor effect in SGC-7901 tumor model with a tumor inhibition rate of 59.57%, and which might be mediated by increasing the levles of TNF-α, Bax and Caspase-3 and reducing the levels of CD34, VEGF, MMP-2, MMP-9 and Bcl-2." (PMID 36463199, 2022). "In particular, propolis promotes the release of TNF-α, IL-6, IL-12, MHC molecules, and IFNs, which are crucial for the activation of NK cells and cytotoxic T lymphocytes and induction of tumor cell death via apoptosis, autophagy, and programmed necrosis." (PMID 36142391, 2022). "NPC-derived mast cells have a high anti-tumor TNF to angiogenic VEGFA ratio, implying high anti-tumor capacity, whereas mast cells in other malignancies are generally pro-tumorigenic." (PMID 35311066, 2022). "While tumor development progressed in mice that received a sham treatment only, the combined action of the cytokines IFN-γ and TNF released by the transferred CD4+ Th1 cells led to senescence induction." (PMID 35326515, 2022). "The mutated Fc-domain can induce activation of NK cells more potently, which mounts robust inflammatory responses including production of IFNγ, TNFα, and IL6 secreted from NK cells to further enhance immune reaction in tumor microenvironment." (PMID 36922936, 2022). "As we know, Th1 cells can produce interferon-γ, interleukin-2, and tumor necrosis factor, which activate macrophages and CD8+T cells to enhance immunity against tumor." (PMID 36505872, 2022). "Notably, the tumor size for the ADP@SWNT/TNFα+irradiation group sharply decreased by more than 50% after treatment with irradiation, which indicated that NIR irradiation could effectively and quickly trigger the light‐heat conversion characteristics of ADP@SWNT/TNFα, thereby damaging the tumor." (PMID 34994069, 2022). "Death receptors such as Fas, DR4, and DR5 belong to the tumor necrosis factor (TNF) superfamily and are important regulators of cell survival, apoptosis, immune response, and tumor growth." (PMID 35745636, 2022). "By enhancing the accumulation of immune checkpoint inhibitors at the tumor site, these novel nanoparticles can promote the localized secretion of cytokines such as TNF-α and INF-γ, and potentiates the anti-tumor immune response in PAAD." (PMID 36263225, 2022). "Significant increases in IFNG, IL‐18, IL‐1β, IL‐8, TNF‐α, TLR4, MyD88, and NF‐κB levels were found in the P. copri and tumour control groups." (PMID 35735103, 2022). "IL-10 production from B cells impairs inflammatory cytokines, including TNF-α and IFN-γ, secretion from cytotoxic T cells to promote tumor growth." (PMID 36033455, 2022). "A recent survey of tumor tissues from patients with GBM correlated the infiltrative character of GBM malignant cells with an increased expression of CCL15, CCL17, CD209, and TNF-α genes." (PMID 35992881, 2022). "The tumor and mesenchymal cells in the TME express multiple chemokines and cytokines (e.g., CXCL1, CXCL2, CXCL5, CXCL6, IL1, IL1β, IL6, IL8, IL17, TNFα, and G-CSF), which are regulated by KRAS, SNAIL, and NOTCH signaling." (PMID 35504900, 2022).